IRF5 (interferon regulatory factor 5)
Diseases named in the same sentence as IRF5 in open-access papers (continued):
Sharing a sentence is not in itself a finding about the gene and the disease.
atherosclerosis (continued). "In summary, the transcription factor Irf5 has a detrimental effect in atherosclerosis by affecting plaque formation and stability through the modulation of macrophage phenotype and function." (PMID 28698173, 2017). "Although there is overwhelming evidence in animal models that 4F improves HDL function and decreases atherosclerosis, our data are the first to suggest that 4F decreases inflammation by inhibiting IRF5 expression and activation." (PMID 23251680, 2012). "Next, we investigated the role of Irf5 in disturbed flow-induced atherosclerosis in vivo and whether it mediates the atherogenic phenotype associated with Aff3ir-ORF2 deficiency." (PMID 40315012, 2025). "This demonstrates IRF5 as a candidate therapeutic target in human atherosclerosis." (PMID 39840103, 2024). "BPA promotes proinflammatory patterns of macrophages through interferon regulatory factor 5 (IRF5) and may influence levels of adipose tissue inflammation, predisposing to atherosclerosis and cardiometabolic diseases." (PMID 39519574, 2024). "We investigated the role of IRF5 in human atherosclerosis and plaque stability." (PMID 35567557, 2022). "Moreover, IRF-5 is essential for maintaining pro-inflammatory CD11c+ macrophages/monocytes within lesions in an experimental atherosclerosis model." (PMID 32038622, 2019). "We investigated the role of IRF5 in atherosclerosis in 2 complementary models." (PMID 28698173, 2017). "Importantly, endothelium-specific supplementation with Aff3ir-ORF2 effectively attenuated endothelial activation and reduced the atherosclerotic plaque area in Apoe-/- mice, suggesting that targeting endothelial Irf5 activation with Aff3ir-ORF2 holds promise for the treatment of atherosclerosis." (PMID 40315012, 2025). "Here, we show that IRF5 and CD11c expression is linked to symptomatic and vulnerable carotid plaques in humans, and that IRF5 drives pro-inflammatory CD11c+ macrophages and inducible plaque rupture in ApoE−/− mice, demonstrating IRF5 as a candidate therapeutic target in human atherosclerosis." (PMID 35567557, 2022). "Furthermore, the percentage of CD11c expression positively correlated with IRF5 expression (r=0.57, P<0.05; Figure VIIB in the online-only Data Supplement), suggesting that similar to murine atherosclerosis there may be a role for IRF5 in regulating CD11c expression in human atherosclerotic disease." (PMID 28698173, 2017). "This gene cluster enriched in ‘proteins involved in non-alcoholic fatty liver disease’ (P = 6.9 × 10−11) and ‘proteins involved in atherosclerosis’ (P = 1.7 × 10−9) whereas IRF5 was absent in the enriched term." (PMID 35567557, 2022). "In the present study, we observed a significant reduction in lesional CD11c staining in the absence of IRF5 in both hypercholesterolemia-induced and LSS-induced murine atherosclerosis models." (PMID 28698173, 2017).
inflammatory bowel disease (18 papers, 2008 to 2023). A spectrum of small and large bowel inflammatory diseases of unknown etiology. "Similarly, a five-nucleotide insertion-deletion polymorphism in the IRF5 promoter was found to be associated with inflammatory bowel disease with the insertion allele enhancing the risk of inflammatory bowel disease." (PMID 25615575, 2015). "Our results thus implicate a function of PYK2 in regulating the inflammatory response in the gut via the IRF5 innate sensing pathway, thereby opening opportunities for related therapeutic interventions for inflammatory bowel diseases and other inflammatory conditions." (PMID 34795257, 2021).
multiple sclerosis (17 papers, 2008 to 2025). A progressive autoimmune disorder affecting the central nervous system resulting in demyelination. "Notably, IRF5 has been identified as a microglia risk gene linked to multiple sclerosis (MS), but its specific role in MS pathogenesis remains unclear." (PMID 40137979, 2025). "Genetic polymorphisms that induce overexpression of IRF-5 mRNA in human auto-immune pathologies like SLE and multiple sclerosis illustrate the link between high IRF-5 expression and type 1 inflammation in human beings." (PMID 22176642, 2011). "However, an in silico analysis of available data obtained by single-cell RNA sequencing of tissues coming from healthy humans and active multiple sclerosis patients showed that Irf5 is downregulated in microglial cells in the pathology (n = 4)." (PMID 40137979, 2025).
Stroke (16 papers, 2018 to 2025). Sudden impairment of blood flow to a part of the brain due to occlusion or rupture of an artery to the brain. "We identified 179 significant SNPs and five common risk genes for RA and stroke (IRF5, RNASET2, ZNF438, UBE2LS, and SYNGR1)." (PMID 39953635, 2025). "While IRF5 CKO led to a decrease only in IL-1β expression after stroke, IRF4 CKO caused up-regulation of both IL-1β and TNF-α in ischemic microglia." (PMID 35963621, 2022). "In conclusion, this study demonstrates the time–course interaction between IRF5/4 and M1/2 microglial phenotypes and provides a new insight into the mechanisms underlying the phenotypic shifts of microglia related to IRF5/4 regulatory axis in response to stroke injury." (PMID 29131464, 2018). "Therefore, we hypothesized that IRF5 mutations are associated with stroke development." (PMID 39953635, 2025). "The different effect of the two Kdms on IRF5 transcripti on suggests that the two X escapee genes impact on stroke outcomes in the aged via different pathways." (PMID 39399684, 2024). "The active effect of Kdm6a on IRF5 transcription is logic to the downstream pro-inflammatory response and worsened stroke injury, but the suppressive effect of Kdm5c on IRF5 seems irrelevant to the downstream outcomes." (PMID 39399684, 2024). "The present study focused on two X chromosome escapee genes, Kdm6a and Kdm5c, and investigated their epigenetic modulation of IRF5/IRF4 via demethylation of H3K27Me3/H3K4Me3 in aged microglia after stroke." (PMID 39399684, 2024). "Several transcription factors, such as STAT1, NF-κB p65, and IRF5, were demonstrated to be involved in proinflammatory microglial polarization after stroke." (PMID 37908012, 2023). "The present study focused on aged microglia, and examined the inflammatory responses and stroke outcomes in IRF5/4 CKO vs. flox aged mice." (PMID 35963621, 2022). "TNF-α/MIP-1α levels significantly decreased, but IL-12p40 significantly increased in IRF5 CKO vs. flox mice after stroke." (PMID 35963621, 2022). "In this study, we used transgenic mouse models to specifically study the effect of conditional knockout (CKO) of IRF4 or IRF5 in microglia on post-stroke inflammation and outcomes." (PMID 35963621, 2022). "Our results showed that MFI of CD68 was significantly downregulated in IRF5 CKO vs. flox mice after stroke; meanwhile CD206 was significantly upregulated by IRF5 CKO." (PMID 35963621, 2022). "Since microglial activation triggers and perpetuates immune responses to stroke and IRF5/IRF4 signaling regulate microglial activation, we next wanted to know if microglial IRF5 or IRF4 signaling impacts on plasma cytokine levels." (PMID 35963621, 2022). "Our previous studies have found IRF5 and IRF4 signaling also regulate microglial activation in neonatal and young adult mice after stroke, with IRF5 being pro-inflammatory and IRF4 anti-inflammatory." (PMID 35963621, 2022). "IRF5 CKO aged mice had improved stroke outcomes; whereas worse outcomes were seen in IRF4 CKO vs. their flox controls." (PMID 35963621, 2022). "Stroke effects on these IRFs’ expression were also age-dependent, as in aged microglia only IRF5 expression increased after stroke in contrast to IRF4 that only increased in young ischemic microglia." (PMID 35963621, 2022). "IRF4 and IRF5 form a regulatory axis that is critical for microglial polarization and immune responses to stroke." (PMID 33712031, 2021). "Abdullah Al Mamun confirmed that the IRF5 also mediates microglial activation after stroke and suggested that microglia appears to have the same IRF5 signaling mechanism as peripheral origin macrophages." (PMID 33392187, 2020). "A recent study found that the expression of IRF5 influenced stroke outcomes, which was related to IRF5 mediated activation of microglia and regulation of neuroinflammation." (PMID 33362784, 2020).
Stroke (continued). "On top of that, it has been shown in animal models that IRF5 is related with the microglial polarization towards a pro-inflammatory state (M1) in response to stroke and in Alzheimer’s disease." (PMID 33255923, 2020). "IRF5/4 signaling also functions in infiltrating monocytes; the present study was focused on microglia that have a central role in post‐stroke inflammation." (PMID 29131464, 2018). "The result showed that the fold increase of IRF5+Iba‐1+ cells was significantly higher at 3 days of stroke and subsequently decreased to the baseline at 10 days." (PMID 29131464, 2018). "The number of double‐positive cells (IRF5+Iba‐1+ or IRF4+Iba‐1+) after stroke was normalized to sham groups." (PMID 29131464, 2018). "Ongoing studies in the laboratory are investigating contributions of IRF5/4 signaling from microglia and/or infiltrating monocytes on stroke outcome with IRF4/5 conditional knockout (CKO) mice and bone marrow chimera mouse models." (PMID 29131464, 2018). "To examine the relationship between IRF5/4 expression and M1/2 microglial activation, we next examined microglial polarization after stroke with flow cytometry." (PMID 29131464, 2018). "In this study, we examined the IRF5/4 signaling in ischemic microglia and evaluated the impacts of the two IRFs on post‐stroke inflammation and outcomes." (PMID 29131464, 2018). "Our results revealed that the IRF5 mRNA level in sorted microglia increased at 3 days of stroke; whereas IRF4 mRNA level exhibited biphasic increases, with a transient rise at 24 h and a peak at 10 days." (PMID 29131464, 2018). "In this study, we utilized a widely accepted animal stroke model (i.e., MCAO) and investigated the relationship of IRF5/4 signaling with microglial M1/M2 phenotype switch, and their correlation with stroke outcomes." (PMID 29131464, 2018). "The time–course of microglial M1/2 polarization seems to be fine‐tuned by endogenous inflammatory signaling pathways, highlighting an important role of IRF5/4 signaling in post‐stroke inflammation." (PMID 29131464, 2018). "Moreover, IRF5 expression can regulate the pro-inflammatory response of microglia and post-stroke inflammation, potentially affecting the recovery of stroke patients." (PMID 39953635, 2025). "However, the mechanism by which Kdm6a/Kdm5c modulates IRF5/4 gene signaling and neuroinflammation after stroke is still elusive." (PMID 39399684, 2024). "We hypothesized that Kdm6a/5c regulate IRF5/4 expression through epigenetic modification of histones, mediate microglial activation/neuroinflammation after stroke, and impact outcomes." (PMID 39399684, 2024). "Our data showed IRF4 or IRF5 had muted function either in the expression of some aged microglial cytokines or in phagocytosis; however, they both impacted on stroke outcomes in a similar pattern as that in young mice." (PMID 35963621, 2022). "Lastly, we evaluated stroke outcomes in these IRF5 or IRF4 CKO aged mice." (PMID 35963621, 2022). "For anti-inflammatory cytokines, a relatively homogenous pattern was seen; IRF5 CKO induced a significant increase in both IL-4 and IL-10 levels, and IRF4 CKO caused significant reduction in IL-4 and a decrease trend in IL-10 level, in stroke groups." (PMID 35963621, 2022). "To investigate whether IRF5 and IRF4 signaling induce similar inflammatory responses to stroke in aged microglia as that in the young, we examined both surface and intracellular inflammatory markers in microglia from IRF5 or IRF4 CKO aged mice at 3d of MCAO." (PMID 35963621, 2022). "Among all IRFs, only IRF4 and IRF5 showed sex-specific expression in aged mice brains after stroke." (PMID 33712031, 2021). "A recently study showed that down-regulation of IRF5 in transient middle cerebral artery occlusion mice attenuated M1, but enhanced M2 activation of microglia, quenched pro-inflammatory responses, and improved stroke outcomes." (PMID 33362784, 2020).
Stroke (continued). "We conclude that microglia phenotypes are dynamic to ischemic stroke, and IRF5/4 signaling may regulate microglial M1/M2 activation and impact on stroke outcomes." (PMID 29131464, 2018). "Firstly, IRF5 expression correlates with microglia M1 polarization and plays an important role in maintaining a pro‐inflammatory microenvironment in the ischemic brain at the early stage of stroke." (PMID 29131464, 2018). "However, when inflammation occurs, the balance is lost by ‘aberrant’ expression of IRF5/4 that synergistically signals to induce the M1 or M2 phenotype, which resultantly impacts on stroke outcomes as shown by our behavior data." (PMID 29131464, 2018). "In the present study, we hypothesized IRF4 CKO worsens while IRF5 CKO improves stroke outcomes." (PMID 35963621, 2022). "We hypothesize that the IRF5/4 regulatory axis also mediates microglial activation after stroke." (PMID 29131464, 2018). "Studies have shown that IRF5 and IRF4 correspond to pro-inflammatory and anti-inflammatory features in microglia after stroke, and IRF5-IRF4 signals form a regulatory axis to balance pro-inflammatory and anti-inflammatory activation in microglia." (PMID 41301548, 2025). "In the present study, we further investigated microglial IRF5 and IRF4 expression in young vs. aged mice after stroke with flow cytometry." (PMID 35963621, 2022). "The pro-inflammatory (TNF-α, IL-1β, IL-6, IL-12 p40, and MIP-1α), and the anti-inflammatory (IL-4 and IL-10) mediators were examined by ELISA in IRF5 or IRF4 CKO aged mice plasma, 3 days after stroke." (PMID 35963621, 2022). "Our previous study has found interferon regulatory factor 5 (IRF5) and 4 (IRF4) regulate neuroinflammation in young stroke mice." (PMID 35963621, 2022). "IRF5 and IRF4 signaling drives microglial pro- and anti-inflammatory response respectively; microglial IRF5 is detrimental and IRF4 beneficial for aged mice in stroke." (PMID 35963621, 2022). "We found aged microglia express higher levels of IRF5 and lower levels of IRF4 than young microglia after stroke." (PMID 35963621, 2022). "Our previous in vivo studies using genetic manipulations in animals have found interferon regulatory factor 5 (IRF5) and 4 (IRF4) play critical roles in mediating microglial pro- and anti-inflammatory response respectively after stroke." (PMID 33573200, 2021). "Consequently, pharmacological reagents could be developed to reduce IRF5 or increase IRF4 expression in microglia after stroke, so that the pro-inflammatory response can be prevented and the anti-inflammatory response trigger earlier to clear the ischemic detriment and boost the tissue repair." (PMID 33317034, 2020). "Recent studies have demonstrated that IRF5 and IRF4 expression in microglia exhibited a “see-saw” pattern and corresponded with pro-and anti-inflammatory profiles, respectively, after stroke." (PMID 33317034, 2020). "To examine IRF5/4 expression in microglia after MCAO, we performed IHC and quantified IRF5/4 colocalization with Iba‐1 at 24 h, 3, 10 and 30 days of stroke." (PMID 29131464, 2018). "Notably, animals with conditional deletion of the IRF5 and IRF4 genes in microglia following stroke showed clear behavioral changes." (PMID 39649720, 2024). "We hypothesized that Kdm6a/5c demethylate H3K27Me3/H3K4Me3 in microglia respectively, and mediate the transcription of interferon regulatory factor 5 (IRF5) and IRF4, leading to microglial pro-inflammatory responses and exacerbated stroke injury." (PMID 39399684, 2024). "For example: Microglial IRF5 CKO mice and microglial IRF4 CKO mice directly alter the activation phenotype of microglia, leading to corresponding changes in inflammatory responses, which in turn affect the prognosis of stroke." (PMID 39649720, 2024). "Our flow data showed IRF5 was significantly expressed in aged vs. young microglia after stroke, as opposed to IRF4 that demonstrated an opposite expression pattern in microglia of the two ages." (PMID 35963621, 2022).
Stroke (continued). "We found aged microglia express more IRF5 and less IRF4 compared to young microglia after stroke." (PMID 35963621, 2022). "Excitingly, our data have indeed confirmed these effects: H3K4me1 and H3K27me1 bind to more IRF4/5 DNA, respectively, in female vs. male microglia after OGD; however, mice with two copies of X have higher IRF5 and lower IRF4 level compared to one X mice after stroke." (PMID 33712031, 2021). "IRF5/4 mRNA ratio also significantly increased at 3 days of stroke; IRF4/5 mRNA ratio showed a trend of transient increase at 24 h which significantly decreased at 3 days and significantly increased at 10 days after stroke." (PMID 29131464, 2018). "Our data suggest Kdm5c’s detrimental effect on stroke injury is independent of IRF5 signaling." (PMID 39399684, 2024). "By using the aged IRF4/IRF5 microglial CKO mouse models, the study aimed to selectively suppress microglial pro-inflammatory activation and promote its anti-inflammatory response, and will potentially help develop new, effective therapeutic strategies against stroke." (PMID 35963621, 2022). "While models of microglial IRF5 and IRF4 CKO mice are particularly helpful in examining the transition between microglial activation states, they might not accurately replicate the intricacy of a real stroke." (PMID 39649720, 2024). "Whether IRF5 and IRF4 also mediate microglial activation after stroke is not known." (PMID 29131464, 2018).